LYG2 (lysozyme g2)
Description:
May act as a potent antibacterial protein that may play a role in the innate immunity.
Synonyms: LYGH; LYGA2; LYSG2
Tractability: Antibody: UniProt places it where antibodies can reach, with high confidence; its Gene Ontology location is reachable by antibodies, with high confidence; UniProt predicts a signal peptide or a membrane-spanning region.
Gene: Protein-coding gene on chromosome 2 (99,242,169 to 99,255,666, reverse strand). Ensembl gene ENSG00000185674.
Subcellular location: Secreted
Gene Ontology:
Molecular function: lysozyme activity; protein binding
Biological process: defense response to bacterium; defense response to Gram-positive bacterium; peptidoglycan catabolic process
Cellular component: extracellular region
Genetic constraint (gnomAD): Loss-of-function variants: 24 observed, 21.06 expected, observed/expected ratio (o/e) 1.14, 90% interval 0.82 to 1.6. The upper end of that interval is the gene's LOEUF score, 1.6, which puts it in group 6 of 6, group 1 being the genes least tolerant of losing a copy. Missense variants: 191 observed, 220.06 expected, observed/expected ratio (o/e) 0.87, 90% interval 0.77 to 0.98. Synonymous variants: 72 observed, 81.35 expected, observed/expected ratio (o/e) 0.89, 90% interval 0.73 to 1.08.
Homologues: Orthologues: chimpanzee LYG2 (99% identical), macaque LYG2 (96% identical), dog LYG2 (83% identical), pig LYG2 (78% identical), rabbit LYG2 (77% identical), rat Lyg2 (77% identical), mouse Lyg2 (75% identical), guinea pig LYG2 (71% identical), zebrafish lygl1 (39% identical), zebrafish zgc:162941 (39% identical), zebrafish lygl2 (35% identical), tropical clawed frog tmem121 (33% identical). Paralogues in human: LYG1 (37% identical).
Diseases named in the same sentence as LYG2 in open-access papers:
LYG2 is named in the same sentence as 2 diseases in open-access papers, as found by Europe PMC text mining. Sharing a sentence is not in itself a finding about the gene and the disease. The quoted sentences say what the papers report.
esophageal cancer (1 paper, 2024). A primary or metastatic malignant neoplasm involving the esophagus. "Here, we report the complete genome sequences of three Porphyromonas gingivalis, one from patient with esophageal cancer (LyEC01), and the other two from periodontally healthy individuals (LyG-1 and LyG-2) in 2021 and 2023." (PMID 38717174, 2024).
infection (4 papers, 2013 to 2024). The state of being infected such as from the introduction of a foreign agent such as serum, vaccine, antigenic substance or organism. "Lysozyme g2 is encoded by the LYG2 gene, which is a lysozyme capable of host defense against infection, and IRG1L is a marker gene of the innate immune system." (PMID 38891577, 2024). "Eight of them (FN1, ALB, CTSL1, OTFB, LYZ, CATHL1, MMP9, LECT2) did not change their expression at the level of transcription and transcripts of 3 of them (RSFR, LYG2, CSTC) even increased following infection." (PMID 28623956, 2017).